ATP6AP2 (ATPase H+ transporting accessory protein 2)
Diseases named in the same sentence as ATP6AP2 in open-access papers (continued):
Sharing a sentence is not in itself a finding about the gene and the disease.
glioblastoma (2 papers, 2004 to 2024). The most malignant astrocytic tumor (WHO grade IV). "In cases of glioblastoma within the TCGA, ATP6AP2, AGTR1, ACE, and AGT had consistent expressions across samples, while AGTR2 and REN were lowly expressed." (PMID 38607073, 2024). "In patient-derived glioblastoma cell lines, ATP6AP2 and AGTR1 were upregulated after chemoradiotherapy and correlated with an increase in HIF1A expression." (PMID 38607073, 2024). "Although this study did not explore the targeting of RAS components, inhibition of RAS receptors such as AGTR1, AGTR2, and ATP6AP2 have been demonstrated to reduce glioblastoma cell growth, proliferation, and/or angiogenesis." (PMID 38607073, 2024). "Progression-free survival (PFS) and overall survival (OS) were compared across TCGA glioblastoma cases, stratified from high and low expression of ATP6AP2, AGTR1, AGTR2, ACE, AGT, and REN genes." (PMID 38607073, 2024). "The combined expression of RAS receptors (ATP6AP2, AGTR1, and AGTR2) was positively associated with gene pathways involved in hypoxia, microvasculature, stem cell plasticity, and the molecular characterisation of glioblastoma subtypes." (PMID 38607073, 2024). "The majority of genes (ATP6AP2, AGTR1, ACE, and AGT) were consistently expressed in glioblastoma cases, with the exception of AGTR2 and REN." (PMID 38607073, 2024). "The expression of RAS receptors (AGTR1, AGTR2, and ATP6AP2) has been demonstrated on the glioblastoma microvasculature, and the inhibition of AGTR1 or AGTR2 reduced glioblastoma cell growth in vitro and in vivo." (PMID 38607073, 2024). "We, thus, examined the relationship of RAS receptors (ATP6AP2, AGTR1, and AGTR2) with TME expression within TCGA glioblastoma samples." (PMID 38607073, 2024). "As ATP6AP2, AGTR1, and AGTR2 are the main receptors in the RAS; this suggests that glioblastomas have a greater capacity to utilise this pathway for their survival." (PMID 38607073, 2024). "The majority of RAS genes (ATP6AP2, AGTR1, AGTR2, and ACE) in our study were highly expressed in glioblastomas compared to LGGs." (PMID 38607073, 2024). "The level of expression of ATP6AP2, AGTR1, AGTR2, and ACE genes in glioblastomas was similar to that observed in a range of other solid tumours and haematological cancers." (PMID 38607073, 2024). "The baseline mRNA expression of RAS genes (ATP6AP2, AGTR1, AGTR2, AGT, ACE, and REN) were explored in 12 patient-derived glioblastoma cell lines." (PMID 38607073, 2024). "Baseline expressions of RAS genes were relatively similar to the TCGA glioblastoma cohort, where REN and AGTR2 were very lowly expressed while ATP6AP2, AGTR1, ACE, and AGT were consistently expressed." (PMID 38607073, 2024). "We studied the expression of RAS-related genes (ATP6AP2, AGTR1, AGTR2, ACE, AGT, and REN) in The Cancer Genome Atlas (TCGA) glioblastoma cohort, their relationship to patient survival, and association with tumour microenvironment pathways." (PMID 38607073, 2024). "ATP6AP2, AGTR1, AGTR2, AGT, and ACE had low frequencies of CNAs (<1%) in glioblastomas; however, REN was altered in 6% of glioblastoma cases." (PMID 38607073, 2024). "Here, we investigated the gene expression of RAS components (ATP6AP2, AGTR1, AGTR2, ACE, AGT, and REN) in glioblastoma patient samples from The Cancer Genome Atlas (TCGA) and their association with survival outcomes and the expression of TME pathways." (PMID 38607073, 2024). "The combination of TMZ + RT resulted in a slight but significant increase in the expression of ATP6AP2, AGTR1, and ACE, while AGT and the lowly expressed AGTR2 and REN remained unchanged across all 12 glioblastoma cell lines." (PMID 38607073, 2024). "When compared to LGG cases, ATP6AP2, AGTR1, and ACE were significantly higher in expression in glioblastomas, with AGTR1 showing the highest change in expression (5.7-fold higher)." (PMID 38607073, 2024). "The majority of glioblastoma cases expressed ATP6AP2, AGTR1, ACE, and AGT but not AGTR2 and REN." (PMID 38607073, 2024).
Insulin resistance (2 papers, 2021 to 2024). Increased resistance towards insulin, that is, diminished effectiveness of insulin in reducing blood glucose levels. "Furthermore, an increase in ATP6AP2 expression and activity correlates with the development of insulin resistance in fructose-fed and obese rats, and subsequent ATP6AP2 inhibition improved glucose tolerance in these animals." (PMID 33326313, 2021).
Intellectual disability (2 papers, 2021 to 2025). "Considering that disturbances in ATP6AP2 have been linked to intellectual disability in humans, investigations focusing on the role of ATP6AP2 could contribute to understanding different brain functions associated with neurogenesis." (PMID 40598350, 2025).
pancreatic cancer (2 papers, 2021 to 2023). "ATP6AP2 encodes the (Pro)renin receptor, which is reported to induce the proliferation of pancreatic cancer cells through Wnt/β-catenin pathways." (PMID 33820913, 2021).
proliferative diabetic retinopathy (2 papers, 2017 to 2022). Advanced retinopathy due to diabetes mellitus characterized by the formation of new vessels in the retina. "Previous works have shown Atp6ap2 expression in fibrovascular tissues of murine and human eyes and indicated that ATP6AP2 is linked to patients with proliferative diabetic retinopathy." (PMID 35998033, 2022). "Initial studies reported that ATP6AP2 regulates angiogenic activity in proliferative diabetic retinopathy." (PMID 35998033, 2022).
adrenocortical carcinomas (1 paper, 2018). "We next sequenced the entire coding region of ATP6AP1 and ATP6AP2 in 103 histologic mimics of GCTs, including paragangliomas (n = 29), schwannomas (n = 25), adrenocortical carcinomas (n = 16), oncocytomas (n = 13), hibernomas (n = 10), and chromophobe renal carcinomas (n = 10)." (PMID 30166553, 2018).
anemia (1 paper, 2023). A reduction in the number of red blood cells, the amount of hemoglobin, and/or the volume of packed red blood cells.
asthma (1 paper, 2023). "Specifically, we sought to examine causal mediation between PBMC key drivers associated with asthma (PRF1 and NKG7 in the NK cell module; CAPZA2, ATP6AP2, CTSS, and RAB3D from the interleukin module) and nasal key drivers associated with asthma (G3BP1 and INADL from the nasal TCA module)." (PMID 37730635, 2023).
Brain atrophy (1 paper, 2023). Partial or complete wasting (loss) of brain tissue that was once present. "Therefore, we believe that the progressive brain atrophy observed in brain MRI may be a characteristic imaging feature of ATP6AP2-related DEE; however, not unique to this disorder as other genetic-metabolic disorders could present a similar finding." (PMID 38274877, 2023).
cardiomyopathy (1 paper, 2014). A disease of the heart muscle or myocardium proper. "On the other hand, deletion of (P)RR, the gene product of the Atp6ap2 gene, results in a lethal cardiomyopathy phenotype which has been attributed to renin- and prorenin-independent vacuolar H+ATPase and Wnt receptor signaling of this gene." (PMID 24587131, 2014).
colon adenocarcinoma (1 paper, 2020). "To further verify those results in big data, we have compared the levels of ATP6AP2 transcripts in tumor tissues of colon adenocarcinoma (COAD) and normal matched tissues, based on the data in the TCGA and GTEx databases." (PMID 32143717, 2020).
developmental and epileptic encephalopathy (1 paper, 2023). An epilepsy associated with developmental impairment that may be due to either the underlying etiology or the superimposed epileptic activity, or both. "We report a patient with developmental and epileptic encephalopathy (DEE) carrying an ATP6AP2 c.858G > A (p.Ala286=) synonymous variant." (PMID 38274877, 2023).
epilepsy syndrome (1 paper, 2021). A syndrome that has a characteristic cluster of clinical features and/or lectroencephalographic (EEG) findings that reflect underlying epileptic activity. "The clinical team prioritized a rare X-linked recessive missense variant in ATP6AP2 due to the gene’s association with epilepsy syndromes, an insight that was not immediately available to the bioinformatician analyzing the case." (PMID 34645894, 2021).
Glucose intolerance (1 paper, 2021). Glucose intolerance (GI) can be defined as dysglycemia that comprises both prediabetes and diabetes. "Intriguingly, ATP6AP2 activation occurs upstream of these pathways, suggesting that ATP6AP2-induced activation of MAPK signaling may be involved in the pathogenesis of glucose intolerance." (PMID 33326313, 2021).
hyperlipidemia (1 paper, 2022). "Compared with VMA21 deficiency (25% increase in LDL-c) and ATP6AP2 deficiency (on average 20% increase in LDL-c), the hyperlipidemia in TMEM199 and CCDC115 deficiency clearly was more pronounced (124% increase in LDL-c)." (PMID 34626841, 2022).
insulinoma (1 paper, 2023). "Other synergistic interactions between Atp6ap2 suppression and various medications should be investigated in the future for the development of more effective strategies to cure insulinoma and pancreatic NETs." (PMID 37286698, 2023). "ATP6AP2 was found to be expressed not only in pancreatic β cells but also in insulinoma cells in all patients." (PMID 37286698, 2023). "Taken together, these results suggested that ATP6AP2 likely plays a role in maintaining the cellular viability of insulinoma cells." (PMID 37286698, 2023). "Here in this study, we investigated the expression profiles of ATP6AP2 in pancreatic endocrine cells, and found that ATP6AP2 is robustly expressed in pancreatic insulinoma cells as well as in normal β cells." (PMID 37286698, 2023). "Knockdown experiments of the Atp6ap2 gene in rat insulinoma-derived INS-1 cells demonstrated decreased cell viability accompanied by a significant increase in apoptotic cells." (PMID 37286698, 2023). "Therefore, it is expected that targeting the Atp6ap2 gene would be an additional option for patients with insulinoma who cannot be cured by current therapies." (PMID 37286698, 2023). "Taken together, these findings suggest that ATP6AP2 plays a role in maintaining cellular homeostasis in insulinoma cells, which could lead to possible therapeutic approaches for endocrine tumors." (PMID 37286698, 2023). "In addition, immunostaining in rat insulinoma cell line INS-1 cells demonstrated ATP6AP2 expression in the cytosol of INS-1 cells." (PMID 37286698, 2023). "Therefore, we analyzed the expression profiles of ATP6AP2 in pancreatic endocrine cells and insulinoma cells, and aimed to clarify whether the knockdown approach for Atp6ap2 can reduce the viability of insulinoma cells, which may lead to the development of novel therapeutic approaches." (PMID 37286698, 2023). "Immunostaining against ATP6AP2 demonstrated the robust expression of ATP6AP2 in insulinoma cells as well as in non-tumor islet cells of the same section, whereas non-tumor cells surrounding the insulinoma cells were not stained with ATP6AP2." (PMID 37286698, 2023). "The expression of ATP6AP2 proteins was clearly detected in insulin-expressing cells of normal islets near the insulinoma lesions and nonfunctioning NETs, whereas it was not or faintly detected in glucagon-expressing cells and somatostatin-expressing cells in the same regions." (PMID 37286698, 2023).
melanoma (1 paper, 2025). A malignant, usually aggressive tumor composed of atypical, neoplastic melanocytes. "ATP6AP2 (the prorenin receptor) has emerged as a biomarker in multiple cancers, including melanoma, and SOD2 has been reported to play context-dependent roles in melanoma, with studies supporting both tumor-suppressive and pro-tumorigenic effects." (PMID 41279463, 2025).
Multiple Organ Failure (1 paper, 2017). A progressive condition usually characterized by combined failure of several organs such as the lungs, liver, kidney, along with some clotting mechanisms, usually postinjury or postoperative. "Our study suggest that disruption of ATP6AP2 is extremely poorly tolerated in the adult, severely affecting various organ systems, resulting in a phenomenon resembling multiple organ failure in humans." (PMID 28851918, 2017). "We have noted that induced adult deletion of ATP6AP2 shares some common manifestations with clinical Multiple Organ Dysfunction Syndrome (MODS, commonly termed “multiple organ failure”)." (PMID 28851918, 2017).
neuroendocrine tumors (1 paper, 2023). "Whereas ATP6AP2 plays an important role in regulating insulin secretion in mouse pancreatic β cells, the expression profiles and roles of ATP6AP2 in human pancreatic endocrine cells and neuroendocrine tumor cells remain unclear." (PMID 37286698, 2023). "Although ATP6AP2 was also expressed in low-grade neuroendocrine tumors, it was not or faintly detected in intermediate- and high-grade neuroendocrine tumors." (PMID 37286698, 2023).
osteoporosis (1 paper, 2024). A condition of reduced bone mass, with decreased cortical thickness and a decrease in the number and size of the trabeculae of cancellous bone (but normal chemical composition), resulting in increased fracture incidence. "The present study provides evidence for ATP6AP2 in Ocn-Cre+ OB-lineage cells to be critical for both OB and OCs differentiation, and thus preventing the development of osteoporosis." (PMID 38811544, 2024).
overnutrition (1 paper, 2013). An imbalanced nutritional status resulting from excessive intake of nutrients. "ATP6AP2 was unchanged in response to both early overnutrition or I/R." (PMID 23383303, 2013).
Spasticity (1 paper, 2013). A motor disorder characterized by a velocity-dependent increase in tonic stretch reflexes with increased muscle tone, exaggerated (hyperexcitable) tendon reflexes. "Mutation in the ATP6AP2/PRR gene (MIM 300556) is a cause of X-linked mental retardation Hedera type (MRXSH) (OMIM # 300423) as well as the newly reported X-linked parkinsonism with spasticity (XPDS) syndrome in humans." (PMID 24223829, 2013).
cancer (15 papers, 2018 to 2025). A tumor composed of atypical neoplastic, often pleomorphic cells that invade other tissues. "Three (CCDC115, ATP6AP1 and ATP6AP2) of the five assembly factor genes are associated with several cancers." (PMID 33680927, 2020). "Loss-of-function mutations of the assembly factor genes are associated with a spectrum of disease symptoms, and the normal function of CCDC115, ATP6AP1, and ATP6AP2 is associated with favorable phenotypes in several cancer types." (PMID 33680927, 2020). "In contrast to the high frequency of likely inactivating ATP6AP1 (61%) and ATP6AP2 (11%) somatic mutations in the GCTs analyzed in this study, mutations affecting these genes were found in only 0.27% and 0.25% of common cancers, respectively." (PMID 30166553, 2018). "Together, these findings suggest that ATP6AP2 plays a pivotal role in cellular pH regulation during therapy-induced senescence, and that altered pH homeostasis appears to be closely associated with immune profile changes in senescent cancer cells." (PMID 37993606, 2023). "The genes encoding CCDC115, ATP6AP1, and ATP6AP2 may play a tumor suppressor role in different cancer types." (PMID 33680927, 2020). "The hub genes ATP6AP2, ACTR1A, SYNM, ZMYND8, CAMTA1, SLC39A3, and DHCR24, are associated with cancer development and progression." (PMID 39757707, 2025). "In previous studies ATP6AP2 was reported to be overexpressed in many cancer types, including pancreatic cancer." (PMID 33820913, 2021). "Suppression of either CD47 or ATP6AP2 alone in MDA-MB-231 cells demonstrated anti-cancer effects, and a double knockdown revealed a synergistic effect and dramatically inhibited tumor development and lung metastasis." (PMID 33603751, 2020). "We then moved to assess the effects of knocking down ATP6AP2 in a variety of cancer cells, and found a similar enhancement of PrCR." (PMID 33603751, 2020). "Additionally, ATP6AP2 has been shown to have gene-to-gene network interactions relating to cancer cell metabolism with PARVA, a member of the Parvins protein family that regulates ECs polarity during embryonic blood vessel development." (PMID 35998033, 2022). "Furthermore, recent reports indicate the full-length form of (pro)renin receptor ((P)RR), a single transmembrane protein encoded by the ATP6AP2 gene, as a novel biomarker for cancer diagnosis, severity evaluation, and prognosis prediction." (PMID 35008363, 2021). "Importantly, however, the role of loss-of-function germline mutations affecting ATP6AP1 and ATP6AP2 remains to be determined and neither ATP6AP1 nor ATP6AP2 have been previously implicated in cancer." (PMID 30166553, 2018). "To determine whether ATP6AP1 and ATP6AP2 loss-of-function mutations are pathognomonic for GCTs, we investigated their presence in 6285 non-hypermutated cancers across 14 common cancer types from The Cancer Genome Atlas (TCGA) studies retrieved from the cBioPortal6." (PMID 30166553, 2018). "In contrast, in our case ATP6AP2 levels were lower in blood from patients with early recurrence and its expression appeared to be somewhat lower in PDAC organoids compared to the non-cancer control." (PMID 33820913, 2021). "In this study, the expression of VMA21 was correlated with the expression of ATP6AP1 and ATP6AP2, although which were not differentially expressed between cancer and noncancer tissues." (PMID 33680927, 2020). "In this study, we identified VMA21 as the only candidate gene showing differential expression between cancer and noncancerous colorectal tissues among five known assembly factor genes (TMEM199, VMA21, CCDC115, ATP6AP1, and ATP6AP2) of the V0 domain." (PMID 33680927, 2020).